TRAV22 (T cell receptor alpha variable 22)
Description:
V region of the variable domain of T cell receptor (TR) alpha chain that participates in the antigen recognition. Alpha-beta T cell receptors are antigen specific receptors which are essential to the immune response and are present on the cell surface of T lymphocytes. Recognize peptide-major histocompatibility (MH) (pMH) complexes that are displayed by antigen presenting cells (APC), a prerequisite for efficient T cell adaptive immunity against pathogens. Binding of alpha-beta TR to pMH complex initiates TR-CD3 clustering on the cell surface and intracellular activation of LCK that phosphorylates the ITAM motifs of CD3G, CD3D, CD3E and CD247 enabling the recruitment of ZAP70. In turn ZAP70 phosphorylates LAT, which recruits numerous signaling molecules to form the LAT signalosome. The LAT signalosome propagates signal branching to three major signaling pathways, the calcium, the mitogen-activated protein kinase (MAPK) kinase and the nuclear factor NF-kappa-B (NF-kB) pathways, leading to the mobilization of transcription factors that are critical for gene expression and essential for T cell growth and differentiation. The T cell repertoire is generated in the thymus, by V-(D)-J rearrangement. This repertoire is then shaped by intrathymic selection events to generate a peripheral T cell pool of self-MH restricted, non-autoaggressive T cells. Post-thymic interaction of alpha-beta TR with the pMH complexes shapes TR structural and functional avidity.
Synonyms: TCRAV13S1; TCRAV22S1
Gene: T-cell receptor variable (V) gene on chromosome 14 (22,070,557 to 22,071,208, forward strand). Ensembl gene ENSG00000211802.
Subcellular location: Cell membrane
Gene Ontology:
Cellular component: plasma membrane
Homologues: Orthologues: mouse Trav13-1 (65% identical), mouse Trav13n-1 (65% identical), mouse Trav13-2 (64% identical), mouse Trav13d-1 (64% identical), mouse Trav13d-4 (64% identical), mouse Trav13d-2 (61% identical), mouse Trav13n-2 (61% identical), mouse Trav13-4-dv7 (60% identical), mouse Trav13n-4 (59% identical), mouse Trav13-5 (57% identical), mouse Trav13d-3 (55% identical), mouse Trav13n-3 (55% identical). Paralogues in human: TRAV41 (43% identical).